MYH11 (myosin heavy chain 11)
Description:
Muscle contraction.
Synonyms: SMMHC; SMHC; SMMS-1; AAT4; FAA4; VSCM2
Tractability: Antibody: the Human Protein Atlas places it where antibodies can reach. PROTAC: ubiquitination databases record sites on it; its protein half-life has been measured.
Gene: Protein-coding gene on chromosome 16 (15,703,135 to 15,858,438, reverse strand). Ensembl gene ENSG00000133392.
Subcellular location: Melanosome
Subcellular location (Human Protein Atlas): Cytosol; Plasma membrane
Pathways (Reactome):
Signal Transduction: RHO GTPases Activate ROCKs; RHO GTPases activate CIT; RHO GTPases activate PAKs; RHO GTPases activate PKNs
Developmental Biology: Developmental Lineage of Mammary Gland Myoepithelial Cells; EPHA-mediated growth cone collapse; Sema4D induced cell migration and growth-cone collapse
Muscle contraction: Smooth Muscle Contraction
Gene Ontology:
Molecular function: protein binding; structural constituent of muscle; actin filament binding; microfilament motor activity; ATP binding; cytoskeletal motor activity
Biological process: cardiac muscle cell development; elastic fiber assembly; actomyosin structure organization; skeletal muscle myosin thick filament assembly; smooth muscle contraction
Cellular component: cytosol; extracellular exosome; plasma membrane; cytoplasm; muscle myosin complex; myosin filament; myosin II complex; melanosome; myosin complex
Genetic constraint (gnomAD): Loss-of-function variants: 79 observed, 252.8 expected, observed/expected ratio (o/e) 0.31, 90% interval 0.26 to 0.38. The upper end of that interval is the gene's LOEUF score, 0.38, which puts it in group 1 of 6, group 1 being the genes least tolerant of losing a copy. Missense variants: 2,157 observed, 2,639.8 expected, observed/expected ratio (o/e) 0.82, 90% interval 0.79 to 0.85. Synonymous variants: 1,071 observed, 1,058.1 expected, observed/expected ratio (o/e) 1.01, 90% interval 0.96 to 1.07.
Gene-disease validity (ClinGen):
ClinGen rates the evidence that MYH11 causes each of these diseases.
familial thoracic aortic aneurysm and aortic dissection (autosomal dominant): Definitive. A rare genetic vascular disease characterized by the familial occurrence of thoracic aortic aneurysm, dissection or dilatation affecting one or more aortic segments (aortic root, ascending aorta, arch or descending aorta) in the absence of any other associated disease.
congenital heart disease (autosomal dominant): Limited. A heart disease that is present at birth.
Homologues: Orthologues: macaque MYH11 (99% identical), dog MYH11 (98% identical), pig MYH11 (98% identical), guinea pig MYH11 (98% identical), chimpanzee MYH11 (97% identical), mouse Myh11 (97% identical), rat Myh11 (94% identical), rabbit MYH11 (94% identical), tropical clawed frog myh11 (85% identical), zebrafish myh11a (81% identical), zebrafish myh11b (68% identical). Paralogues in human: MYH10 (76% identical), MYH9 (76% identical), MYH14 (63% identical), MYH7 (41% identical), MYH3 (41% identical), MYH8 (41% identical), MYH1 (41% identical), MYH2 (41% identical), MYH4 (41% identical), MYH6 (41% identical), MYH7B (41% identical), MYH13 (40% identical), and 32 more.
Diseases named in the same sentence as MYH11 in open-access papers:
MYH11 is named in the same sentence as 225 diseases in open-access papers, as found by Europe PMC text mining. Sharing a sentence is not in itself a finding about the gene and the disease. The quoted sentences say what the papers report.
acute myeloid leukemia (80 papers, 2008 to 2026). Acute myeloid leukemia (AML) is a group of neoplasms arising from precursor cells committed to the myeloid cell-line differentiation. "Core binding factor acute myeloid leukemia (CBF-AML) includes AML cases harboring RUNX1::RUNX1T1 or CBFβ::MYH11 fusion genes, which are classified as a favorable-risk group." (PMID 38802593, 2024). "Patient 4 (P4) F/58Y and 5 (P5) F/66Y were acute myeloid leukaemia (AML) patients with rare CBFB::MYH11 Type G and I fusion transcripts respectively." (PMID 38493200, 2024). "A retroviral insertion mutagenesis study showed that M1AP synergized with Cbfb (core-binding factor)-MYH11 (myosin, heavy chain 11) translocation during the onset of acute myeloid leukemia." (PMID 34604049, 2021). "The inversion of the MYH11 locus is one of the most common chromosomal aberrations in acute myeloid leukemia." (PMID 33747044, 2021). "Myosin heavy chain 11 (Myh11) has been reportedly connected to plenty of human diseases, such as gastric cancer, colorectal cancer and acute myeloid leukemia." (PMID 32578852, 2020). "Inversion at the MYH11 locus is one of the most frequent chromosomal aberrations found in acute myeloid leukemia." (PMID 18796164, 2008). "We report a unique pediatric acute myeloid leukemia (AML) case characterized by a CBFB::MYH11 fusion located on a supernumerary ring chromosome 16." (PMID 41300735, 2025). "Indeed chromosomal translocations such as AML1-ETO, PML-RARA and CBFβ-MYH11, which cause childhood Acute Myeloid Leukemia (AML), frequently arise in utero as demonstrated by the high prevalence of such mutations in neonatal blood samples, and may therefore impact fetal hematopoiesis." (PMID 29300724, 2018). "In this study, we performed an integrated analysis of bulk and single-cell DNA sequencing data of core-binding factor acute myeloid leukemia patients, defined by the presence of a RUNX1::RUNX1T1 or CBFB::MYH11 fusion gene." (PMID 41152985, 2025). "In acute myeloid leukemia (AML), CBFB is one of the most targeted genes, with most of the genetic alterations being fusions, such as to the MYH11 gene." (PMID 33945523, 2021). "MYH11 is closely related to the survival of HNSCC, acute myeloid leukemia, colorectal cancer, bladder cancer, and other tumors." (PMID 34631779, 2021). "The fusion genes CBFB/MYH11 and RUNX1/RUNX1T1 block differentiation through disruption of the core binding factor (CBF) complex and are found in 10–15% of adult de novo acute myeloid leukemia (AML) cases." (PMID 31896782, 2020). "According to multiplex PCR, all 135 screened samples were negative for the most frequent PGF of B-lineage ALL: TEL-AML1, E2A-PBX, MLL-AF4, and BCR-ABL (p190) and for the most frequent PGF of acute myeloid leukemia (AML): AML-ETO, PML-RARA, and CBFβ-MYH11." (PMID 24621554, 2014). "Additionally, conditions such as acute myeloid leukemia (AML) with RUNX1::RUNX1T1 fusion, AML with CBFB::MYH11 fusion, myeloid/lymphoid neoplasms with eosinophilia and specific gene rearrangements, and the blast phase of chronic myeloid leukemia (CML) must be excluded from the diagnosis." (PMID 41366999, 2025).
leukemia (54 papers, 2008 to 2026). A malignant (clonal) hematologic disorder, involving hematopoietic stem cells and characterized by the presence of primitive or atypical myeloid or lymphoid cells in the bone marrow and the blood. "This suggests that Cbfb-MYH11–expressing cells with one allele of RUNX1-R188Q are still able to generate the pre-leukemic AMPs but fail to progress to full-blown leukemia." (PMID 40763310, 2025). "Study showed that GATA2 activity affected the mutational dynamics of leukemia in Cbfb-MYH11 knockin mice." (PMID 34485141, 2021). "Core inding factor (CBF) leukemia subtypes, which includes leukemias harboring fusion genes CBFB/MYH11 or RUNX1/RUNX1T1, are associated with younger age and range from 20% in pediatric to less than 5% in older AML patients." (PMID 34947882, 2021). "Exon 8 frameshift mutations were highly associated with CBFB/MYH11-rearranged leukemia, while point mutations affecting position D816 were correlated with RUNX1/RUNX1T1 leukemia." (PMID 31896782, 2020). "KIT is a well-established regulator of leukemia cell survival and activating mutations in KIT cooperate with Cbfb-MYH11 during leukemia development." (PMID 30742053, 2019). "Plag1 and its homologue, Plagl2, have also previously been implicated in leukemia, being observed as candidate cooperating oncogenes in a retroviral insertion screen with the CBFβ-MYH11 product of the inv16 gene rearrangement." (PMID 30890554, 2019). "However, despite slower development of leukemia, the Cbfb-MYH11 Gata2-deficient mice showed a more aggressive phenotype at the leukemic stage." (PMID 31817911, 2019). "To investigate the impact of RUNX1-R188Q on Cbfb-MYH11–induced leukemia, we examined the AMP population in the bone marrow, as this cell population plays a critical role in Cbfb-MYH11–induced leukemia." (PMID 40763310, 2025). "Cbfb-MYH11-mDE was unable to induce leukemia, whereas CBFB-MYH11-ΔHABD unexpectedly accelerated leukemia development." (PMID 40763310, 2025). "We also conducted bulk RNA-Seq on LK cells isolated from mice expressing Cbfb-MYH11 or its related mutant to identify genes involved in Cbfb-MYH11–induced leukemia development." (PMID 40763310, 2025). "Conditional Cbfb-MYH11-ΔHABD knockin mice exhibit a leukemia profile similar to that of Cbfb-MYH11 mice." (PMID 40763310, 2025). "The ELN also stipulates suitable molecular biomarkers, highlighting leukemia initiating variants (e.g., NPM1, CBFB::MYH11, RUNX1::RUNX1T1, PML::RARA) essential in disease monitoring." (PMID 38891959, 2024). "The heterozygous knockout of GATA2+/− in mice caused the inhibition of abnormal myeloid-progenitor-cell proliferation and differentiation and leukemia inhibition in Cbfb-MYH11 transgenic mice." (PMID 35269883, 2022). "Previously, we showed that IL1RL1, the receptor of IL-33, is highly expressed in leukemia cells expressing Cbfb-MYH11, and exogenous treatment with IL-33 promoted the survival of both primary mouse leukemia cells and human AML cell lines in vitro." (PMID 33324412, 2020). "Previously, we used a mouse knock-in model to show that Cbfb-MYH11 induces changes in gene expression and results in the accumulation of abnormal myeloid cells, a subset of which are enriched for leukemia stem cell (LSC) activity." (PMID 30742053, 2019). "We found that treatment of Cbfb-MYH11+ leukemia cells with exogenous IL-33, the only known IL1RL1 ligand, reduced apoptosis and proliferation, and increased serial replating ability." (PMID 30742053, 2019). "Collectively, our results indicate that IL1RL1 is dynamically expressed in Cbfb-MYH11+ leukemia cells and promotes their survival." (PMID 30742053, 2019). "Chd7 deficiency in Chd7f/fMx1-CreCbfb+/56M mice, which expresses the Cbfb-MYH11 fusion gene, delayed Cbfb–MYH11-induced leukemia in both primary and transplanted mice." (PMID 31817911, 2019).
leukemia (continued). "Expression of CBFβ-MYH11 is able to disrupt normal myeloid differentiation, predispose for AML initiation, and cause full leukemia transformation upon the acquisition of additional genetic changes." (PMID 30850577, 2019). "AI-10-49 is of particular interest for treatment of (inv16) AML as it inhibits RUNX1 binding to CSF1R, RUNX3 and CEBPa promoter targets and also strongly increases mice survival in CBFβ-MYH11 murine leukemia cell models by reducing leukemia burden." (PMID 29921764, 2018). "Genetic evidence, using Cbfb+/MYH11 knock-in mice, revealed that RUNX activity is essential for CBFβ–SMMHC-associated leukemia function." (PMID 29755956, 2018). "Notably, these pathways were also enriched in the DEGs identified in the AMP population between Mx1-CreCbfb+/56M and Runx1+/R188QMx1-CreCbfb+/56M mice, further emphasizing their critical role in Cbfb-MYH11–induced leukemia." (PMID 40763310, 2025). "We firstly generated conditional Cbfb-MYH11-ΔHABD knockin mice to overcome the limitations of the previous chimeric mouse model, and we found that the conditional Cbfb-MYH11-ΔHABD knockin mice exhibited a leukemia profile similar to that of Cbfb-MYH11 mice albeit with longer latency." (PMID 40763310, 2025). "Previously, we demonstrated that exogenous IL-33 increases the expression of IL-6 using primary mouse leukemia cells expressing Cbfb-MYH11, which indicates that IL-33 may induce cytokine release to inhibit AML cell apoptosis." (PMID 33324412, 2020). "Heterozygous knockout of Gata2 in Cbfb-MYH11 mice delayed leukemia onset." (PMID 31817911, 2019). "To test whether IL1RL1 and KIT can be used to isolate cells with LSC activity in vivo, we performed LDA using leukemia samples from three independent Cbfb-MYH11 expressing mice." (PMID 30742053, 2019). "Thus, in this report we examined the expression of IL1RL1 in the LSC-enriched CSF2RB− population, and the effect of the IL1RL1 ligand, IL-33, on Cbfb-MYH11 expressing leukemia cells." (PMID 30742053, 2019). "Furthermore, a higher incidence of leukemia in CBFβ-MYH11 chimeras compared to normal chimeras when exposed to ENU mutagenesis has also been observed." (PMID 18671852, 2008). "As a consequence, GATA2 alone is not sufficient to inhibit CBFβ-MYH11-caused leukemia, and it maybe has greater functional relevance only in context with overexpression of other regulators like KLF1." (PMID 30850577, 2019). "To examine whether the differences in behavior among the different LSC sub-populations could be due to differences in Cbfb-MYH11 expression, we performed RT-PCR for the fusion gene on sorted leukemia cells and found that that Cbfb-MYH11 expression is similar among each of the sorted sub-population." (PMID 30742053, 2019). "An “Eprobe leukemia panel kit” based on this Eprobe mediated RT-qPCR assay, equipped with synthetic quantitative standard RNAs with strict quality control and additional targets including CBFb-MYH11, ETV6-AML1, MLL-AF4, and MLL-AF9 rearrangements is currently under development." (PMID 30281597, 2018). "Consequently, the MYH11-CBFB fusion is thought to be dispensable for leukemia development." (PMID 27542261, 2016). "Our recent data suggested that Runx1 is indispensable for Cbfb-MYH11–induced leukemogenesis, functioning cooperatively with CBFβ-SMMHC to regulate critical genes for leukemia initiation." (PMID 40763310, 2025). "Using a knock-in mouse model of inversion AML, we previously demonstrated that the fusion gene, Cbfb-MYH11, induces the expression of IL-33 receptor, IL1RL1, on leukaemia cells." (PMID 34435521, 2021). "In summary, our study provides a detailed overview of cooperating mutations in one of the largest adult CBF leukemia cohorts so far and highlights fundamental differences between CBFB/MYH11- and RUNX1/RUNX1T1-rearranged leukemia." (PMID 31896782, 2020).
leukemia (continued). "The established system contains dox-inducible CBFβ-MYH11 and we expressed the oncoprotein during differentiation towards the granulocytic, monocytic, and megakaryocyte lineage, allowing the investigation of the effects of CBFβ-MYH11 in the absence of additional leukemia driver mutations." (PMID 30850577, 2019). "In the present study, we show that expression of the leukemogenic fusion gene Cbfb-MYH11 induces expression of IL1RL1 prior to CSF2RB, implying that IL1RL1 marks an earlier stage of leukemia development." (PMID 30742053, 2019). "This study also identified immune disease-related genes associated with somatic mutations such as MYD88 and BCL10 in NF-κB signaling, CD79B, PAX5, and BCR in B-cell development, and MYH11, RUNX1, and TET2 in leukemia." (PMID 29937999, 2018). "As immune disease-related genes, MYD88 (81.4%) and BCL10 (25.9%) in NF-ĸB signaling, CD79B (59.2%), PAX5 (22.2%), and BCR (7.4%) in B-cell development, and MYH11 (25.9%), RUNX1 (7.4%), and TET2 (7.4%) in leukemia were observed." (PMID 29937999, 2018). "And CBFbeta-MYH11 occurred more prevalently in HOVON/SAKK AML- 42 and ECOG1900 trials (50.0 and 54.3% of CBF leukemia, respectively) than in Chinese and Japanese trials (20.1 and 20.8%, respectively)." (PMID 29427994, 2018). "In addition, a total of 17 patients with CBF leukemia (12 AML with RUNX1-RUNX1T1 gene fusion and 5 AML with CBFβ-MYH11 gene fusion) were confirmed via NGS analysis." (PMID 35563085, 2022). "We found that IL-33 significantly decreased BrdU incorporation, as well as the percentage of cells in S-phase, indicating that IL-33 does not induce proliferation in Cbfb-MYH11+ leukemia cells." (PMID 30742053, 2019). "With regard to genetic abnormalities, the incidence of CBF leukemia was significantly lower in e/s‐AML patients as compared with young patients (7.1% vs 14.7%, P = .013 for RUNX1‐RUNX1TI and 2.6% vs 7.4%, P = .038 for CBFβ‐MYH11)." (PMID 31348835, 2019). "To examine if IL1RL1 could be a marker for less differentiated leukemia cells, we characterized the expression of IL1RL1 after induction of Cbfb-MYH11 but before leukemia development." (PMID 30742053, 2019). "Importantly, mice with conditional knockin of Cbfb-MYH11 over Runx1-null background did not develop leukemia, suggesting that Runx1 is indispensable for leukemogenesis by Cbfb-MYH11." (PMID 40763310, 2025). "Moreover, unsupervised hierarchical clustering based on HOX expression divided the leukemias into five main clusters characterized by the presence or absence of prevalent gene rearrangements, i.e., PML-RARa, RUNX1-RUNX1T1(AML1-ETO), CBFb-MYH11 and MLL alterations." (PMID 25539595, 2014).